HMGB1 (high mobility group box 1)
Diseases named in the same sentence as HMGB1 in open-access papers (continued):
Sharing a sentence is not in itself a finding about the gene and the disease.
Alzheimer disease (61 papers, 2016 to 2025). A progressive, neurodegenerative disease characterized by loss of function and death of nerve cells in several areas of the brain leading to loss of cognitive function such as memory and language. "HMGB1 is a prototypical danger-associated molecular pattern (DAMP) molecule that co-localizes with amyloid beta (Aβ) in the brains of patients with Alzheimer’s disease." (PMID 38247880, 2024). "Recently, it was additionally showed that HMGB1 is a critical pathogenic molecule leading to neurite degeneration and innate-immune activation during Alzheimer's disease pathology." (PMID 28567000, 2017). "Similarly, antibody-mediated neutralization of HMGB1 has been shown to attenuate glial cell activation and prevent neuron loss in models of both Alzheimer’s disease and Parkinson’s disease." (PMID 38713518, 2024). "As well as binding AGEs, RAGE is also activated by calgranulins, amyloid-beta (Aβ) peptides, associated with Alzheimer’s disease, and high-mobility group protein 1 (HMGB1), a chromatin protein which functions in the nucleus, but is released by immune cells as a leaderless cytokine." (PMID 33585492, 2021). "In Alzheimer’s disease, HMGB1 interacts with beta-amyloid (Aβ), promoting the formation of Aβ plaques and triggering axonal degradation through the TLR4-MARCKS signaling pathway, which is one of the hallmarks of early neurodegeneration." (PMID 39507236, 2024). "Studies have shown that therapies targeting HMGB1 have significant effects in Alzheimer’s disease models, reducing neurodegeneration and improving cognitive function." (PMID 39507236, 2024). "Inhibiting HMGB1 expression improves cognitive function in aged and Alzheimer’s disease mouse models, highlighting the therapeutic potential of targeting HMGB1 in age-related cognitive decline." (PMID 39507236, 2024). "HMGB1 is also involved in cognitive impairment-related diseases, such as Alzheimer’s disease (AD) and traumatic brain injury (TBI)." (PMID 36906561, 2023). "A number of approaches have been proposed to block the HMGB1/RAGE axis to treat inflammatory diseases such as Alzheimer’s disease, ALI, cardiovascular diseases, osteoarthritis, and others." (PMID 36364135, 2022). "Analyzing four models of frontotemporal lobar degeneration and four models of Alzheimer’s disease, they observe conserved signaling networks and confirm a therapeutic effect of human anti-HMGB1, demonstrating the utility of the approach." (PMID 34385591, 2021). "Increased levels of endogenous HMGB1 have also been detected in neurodegenerative diseases, such as Alzheimer’s disease, Parkinson’s disease and multiple sclerosis, contributing to chronic neurodegeneration and progression of neuroinflammation." (PMID 32486462, 2020). "As an inhibitor of high mobility group box 1 (HMGB1), a pro-inflammatory protein, GA shows therapeutic potential in HMGB1-mediated conditions such as traumatic brain injury, neuroinflammation, seizures, Alzheimer’s disease, multiple sclerosis and PD." (PMID 40999534, 2025). "Yet, our findings that HMGB1 can directly impair OL maturation may also have implications for Alzheimer’s disease and frontotemporal dementia, where HMGB1 released from astrocytes has been reported to promote senescence in addition to neuropathology." (PMID 35573828, 2022). "A recently developed HMGB1-specific mAb blocking the TLR4-binding epitope of HMGB1 has demonstrated beneficial therapeutic effects in mouse models of preclinical Alzheimer ́s disease, and other neutralizing anti-HMGB1 mAbs exerted neuroprotection in a rat model of Parkinson ́s disease." (PMID 34943830, 2021). "In Alzheimer’s Disease, secreted HMGB1 impairs memory through pattern recognition receptors that engage the innate immune response; furthermore, the secreted HMGB1 can aggregate to neuritic plaques and then bind Aβ, which in turn inhibits the phagocytosis and degradation of Aβ by microglial cells." (PMID 34685561, 2021).
Alzheimer disease (continued). "In recent days, HMGB1 has been extensively explored in several HMGB1 mediated neurological pathologies including Epileptogenesis, Parkinson’s disease (PD), Alzheimer’s disease (AD), Multiple sclerosis (MS) and ALS and Brain injuries." (PMID 33732146, 2020). "In addition, a study of Alzheimer's disease showed that HMGB1 stably binds to amyloid‐beta (Aβ) peptides to suppress Aβ phagocytosis by microglia (Mallama, Mccoysimandle, & Cianciotto, 2017)." (PMID 29670828, 2018). "miR-129-5p has been suggested to play roles in Alzheimer’s disease, potentially involving the regulation of autophagy, neuroinflammation, and neuronal cell death through targeting amyloid precursor protein (APP), high-mobility group box 1 (HMGB1), and yes-associated protein 1 (YAP1) genes." (PMID 38195609, 2024). "HMGB1 also appears to be involved in various neurodegenerative diseases, such as Parkinson and Alzheimer Disease (AD)." (PMID 31819042, 2019). "While DAMPs have previously been shown to contribute to inflammatory diseases such as Parkinson's and Alzheimer's disease, studies on DAMPs contributing to DMD such as HMGB1 are limited." (PMID 39158383, 2024). "In these diseases, HMGB1, as a DAMP, plays a critical role in neurodegenerative conditions such as Alzheimer’s disease and Parkinson’s disease by activating inflammatory signaling pathways." (PMID 39507236, 2024). "Treatment of APOE4-tauopathy mice with HMGB1 inhibitors effectively blocked the intraneuronal translocation and release of HMGB1 and ameliorated APOE4-driven Alzheimer’s disease pathologies." (PMID 37863057, 2023). "The suppression of HMGB1, TLR, and RAGE was shown to halt the progression of amyloid-beta (Aß) loading in Alzheimer’s disease (AD) and diabetes-related dementia." (PMID 37109411, 2023). "Current studies show that the regulation of HMGB1 on local inflammation can effectively change the occurrence, development, and prognosis of diseases such as stroke, TBI, PD, epilepsy, and Alzheimer’s disease (AD) via the regulation of microglial polarization." (PMID 35978950, 2022). "This antibody impeded HMGB1-mediated TLR4-dependent biological effects in vitro and exerted beneficial therapeutic effects in a preclinical model of Alzheimer ́s disease." (PMID 34943830, 2021). "Finally, in a mouse model of Alzheimer’s disease (5xFAD), OL suppresses the activation of NLRP3 inflammasomes and RAGE/HMGB1 pathways." (PMID 39456822, 2024). "Moreover, oleocanthal suppressed the receptor for advanced glycation end products/high mobility group box 1 (RAGE/HMGB1) pathway, which is also involved in the activation of the NF-κB pathway and related neuroinflammation in Alzheimer’s disease." (PMID 38139152, 2023). "However, the cellular and subcellular distribution of HMGB1 in relation to the pathology of Alzheimer’s disease has not yet been studied in detail." (PMID 38247880, 2024).
cervical carcinoma (60 papers, 2012 to 2025). A carcinoma arising from either the exocervical squamous epithelium or the endocervical glandular epithelium. "In a univariate analysis, a significant recurrence of HPV infection is linked to elevated HMGB1 protein in cervical cancer samples." (PMID 39583399, 2024). "It promotes tumorigenesis and radioresistance of cervical cancer by targeting HMGB1-RB axis and causes polarization of macrophages by mediating miR-375." (PMID 31426855, 2019). "Elevated HMGB1 protein in cervical carcinoma samples was associated with a high recurrence of HPV infection in univariate analysis (p < 0.05)." (PMID 24837834, 2014). "The diagnostic sensitivity and specificity of HMGB1 were; 71% and 67% in gastric cancer and 71.6% and 78% in cervical cancer, respectively." (PMID 22496788, 2012). "It reminds that the expression of HMGB1 may be associated with proliferation and metastasis of cervical cancer cells." (PMID 30962261, 2019). "Based on these assays, HMGB1 is associated with cell migration of cervical cancer cells." (PMID 30962261, 2019). "In the present study, our team identified that the expression of HMGB1 was decreased due to enhanced expression of miR-142 in cervical cancer cells, and we demonstrated an inverse association between the miR-142 expression and HMGB1 mRNA by detecting cervical cancer tissues." (PMID 27829233, 2017). "In view of these results, our team made a hypothesis that HMGB1 gene might be implicated in biological processes of miR-142 in the progressions of cervical cancer." (PMID 27829233, 2017). "In summary, HMGB1 has a crucial role in the processes involved in chronic inflammation caused by HPV infection in cervical cancer and may contribute to tumor progression." (PMID 24837834, 2014). "Further studies investigating the mechanisms underlying the action of HMGB1 in cervical carcinoma may be warranted." (PMID 24837834, 2014). "Cisplatin resistance due to cytoplasmic HMGB1 was also reported in other cancers, such as cervical cancer, ovarian cancer, and leukemia." (PMID 40561066, 2025). "Liquiritin exerts immunogenic cell death (ICD) effects on human cervical cancer by inducing HMGB1 release, ATP secretion, and calreticulin exposure through ER stress." (PMID 40002335, 2025). "The findings demonstrate how HMGB1 enhances the responsiveness of cervical cancer cells to cisplatin therapy." (PMID 38601753, 2024). "miR-1284 exhibited a characteristic dose-dependent cytotoxic effect on cervical cancer cells as a result of reducing HMGB1 levels." (PMID 39346915, 2024). "In the present study, the prevalence of the CEA, CYFRA 21-1 proteins, SCCA, and HMGB1 in the serum of cervical cancer patients was only regarded." (PMID 39583399, 2024). "Despite the scarcity of studies on HMGB1 in EC, research indicates a strong link with its resistance to chemotherapy in cases of ovarian and cervical cancer." (PMID 38601753, 2024). "HMGB1 suppression increases cell proliferation and invasion, but decreases sensitivity to radiation therapy in cervical cancer, and HMGB1 induction exerts the opposite effects." (PMID 38725632, 2024). "Xia and colleagues Discovered a temporal escalation in HMGB1 expression in cervical cancer cells following cisplatin treatment, coupled with heightened autophagy activity." (PMID 38601753, 2024). "HMGB1 can promote the immune escape of cervical cancer by activating Tregs or facilitating Th2 polarization, so as to accelerate the metastasis of cervical cancer." (PMID 38651153, 2024). "Gly has been shown to be able to block HMGB1 by direct binding to it, both in cervical cancer cells and in other tissues and in animals." (PMID 38138866, 2023). "While miR-1284 downregulation in cervical cancer tissues and cell lines correlated with poor survival, the miR-1284/HMGB1 axis suppressed proliferation and invasion." (PMID 34073766, 2021).
cervical carcinoma (continued). "HMGB1 is a well-characterized oncogene that is involved in chronic inflammation, progressive tumorigenesis, active metastasis, and therapy resistance of cervical cancer tissues." (PMID 33805515, 2021). "The reverse association of the high mobility group box 1 (HMGB1) with miR-34a, miR-1284, and miR-142 is identified in the cervical cancer cells." (PMID 33805515, 2021). "In the course of our study a physical interaction between SEPT9 and HMGB1 in cervix cancer was reported further validating our results." (PMID 34572914, 2021). "In the course of our study a direct interaction between SEPT9 and HMGB1 in cervix cancer was reported further validating our results." (PMID 34572914, 2021). "Co-delivery of MiR-1284 and CDDP showed a synergistic effect in suppressing the cervical cancer cells by the downregulation of HMGB1." (PMID 32185543, 2020). "Further, HO-AAVPA was evaluated in the SiHa cervical cancer cell line to measure its cytotoxicity and to identified the HMGB1 localization; after the treatments, the levels of superoxide anions (O2−·) were measured." (PMID 32824279, 2020). "A preliminary validation has been made to explore the possible correlation factors with HMGB1 that promote migration of cervical cancer cells." (PMID 30962261, 2019). "FIGO stage, lymph mode metastasis, and HMGB1 expression were independent predictors of a poorer prognosis of patients with cervical cancer." (PMID 30962261, 2019). "A total of 862 DEGs that exhibited the same expression trends in two profiles were identified in the high HMGB1 expression group in cervical cancer." (PMID 30962261, 2019). "Immunohistochemical analysis of HMGB1 was performed on 239 cases of cervical cancer samples to investigate its possible correlation with clinicopathological characteristics and outcomes." (PMID 30962261, 2019). "The present study is to investigate the prognostic value of HMGB1 expression in cervical cancer and to further understand its role in the development of cervical cancer." (PMID 30962261, 2019). "Up- and downregulation of SEPT9 affected the biological behavior of cervical cancer cells through the regulation of HMGB1." (PMID 31426855, 2019). "Taken together, these results suggest that HMGB1 plays an important role in colony formation potential of cervical cancer cell lines." (PMID 29472602, 2018). "Functional analysis also showed that HMGB1 expression is important for the proliferative and tumorigenic potential of cervical cancer cell lines." (PMID 29472602, 2018). "It should be noted that HMGB1 was also involved in cancer cell growth, invasiveness and apoptosis of cervical cancer." (PMID 27829233, 2017). "In conclusion, our present study identified miR-142 as a tumor suppressor in the progression of cervical cancer, including cell growth, invasiveness and apoptosis via its direct target HMGB1." (PMID 27829233, 2017). "Next, our team demonstrated HMGB1 gene as a direct target of miR-142 in cervical cancer cells, and verified that the inhibitory effect of miR-142 on cervical cancer cells was mediated by the regulation of expression of HMGB1." (PMID 27829233, 2017). "Overexpression of HMGB1 has also been observed in cervical cancer and a correlation has been found between HMGB1 expression and malignant tumor phenotypes, such as metastasis and recurrence." (PMID 24837834, 2014). "HMGB1 expression tends to increase as cervical cancer progresses and it was found to be significantly correlated to FIGO stage and lymph node metastasis." (PMID 24837834, 2014). "We investigated the significance of high- mobility group box1 (HMGB1) and T-cell-mediated immunity and prognostic value in cervical cancer." (PMID 24837834, 2014). "SCCA and HMGB1 expression were positively correlated, suggesting that HMGB1 may serve as a biomarker for assessing the biological actions and prognosis of cervical cancer." (PMID 39583399, 2024).
cervical carcinoma (continued). "However, HMGB1 secretion during cervical cancer progression impairs the antiviral response by inhibiting IFNα secretion and increasing ICOSL (Inducible T Cell Costimulator Ligand) expression by plasmacytoid dendritic cells (pDCs)." (PMID 38138866, 2023). "The literature also indicates that HMGB1 is highly expressed in cervical cancer tissues." (PMID 35379200, 2022). "LncRNA NNT-AS1 contributed to CDDP resistance in cervical cancer by the miR-186/HMGB1 pathway." (PMID 34746018, 2021). "A recent report showed that HMGB1 may be an important factor in the development of chemoresistance in cervical cancer." (PMID 32328193, 2020). "Moreover, ALA-PDT significantly downregulated miR-34a and upregulated HMGB1 expression levels in cervical cancer tissues." (PMID 32528867, 2020). "Notably, MiR-1284 showed a typical concentration-dependent cell killing effect in the cervical cancer cells owing to the downregulation of HMGB1." (PMID 32185543, 2020). "Furthermore, its antiproliferative effect on the cervical cancer cell line (SiHa) and the translocation of HMGB1 and ROS production were evaluated." (PMID 32824279, 2020). "Results clearly highlight our expectation that downregulation of HMGB1 could be directly related to the proliferation of cervical cancer cells." (PMID 32185543, 2020). "Results of the present study may help to further understand the effects of HMGB1 in cervical cancer during its progression and how it may lead to poor survivorship and reveal potential targets for diagnostic and therapeutic manipulation." (PMID 30962261, 2019). "The high HMGB1 level may play a role in the development of cervical cancer or even be a key point of oncogenesis, making it a potential target for cancer therapy." (PMID 30962261, 2019). "To examine the mechanism by which SEPT9 regulates radio-sensitivity in cervical cancer cells, we explored the association between SEPT9 and HMGB1, and were pleasantly surprised to find that SEPT9 was negatively correlated to HMGB1 in cervical cancer cell lines." (PMID 31426855, 2019). "The pathway-related networks provide us with a number of potential genes or pathways that may relate to proliferation and metastasis functions of HMGB1 in cervical cancer; hence, the call for further investigations." (PMID 30962261, 2019). "HMGB1 is a useful prognostic indicator and a potential biomarker of cervical cancer." (PMID 30962261, 2019). "Our results show that cervical cancer cell lines express high levels of HMGB1." (PMID 29472602, 2018). "The results presented here support the hypothesis that HMGB1 silencing reduces cell viability, proliferation, and colony formation capacity of cervical cancer cell lines." (PMID 29472602, 2018). "Subsequent Kaplan-Meier analysis of patients with cervical carcinoma from GEPIA demonstrated that patients with high HMGB1 expression levels displayed significantly poorer overall survival (p = 0.029) and disease free survival (p = 0.012) than those with low HMGB1 expression levels." (PMID 29844348, 2018). "Gene expression analysis results showed that HMGB1 is upregulated in cervical cancer cell lines." (PMID 29472602, 2018). "These phenomena indicate that miR-142- HMGB1 pathway may be a potential therapy target in the treatment of cervical cancer." (PMID 27829233, 2017). "HMGB1 has been demonstrated to be over-expressed in cervical cancer tissues." (PMID 27829233, 2017). "The dual luciferase assay strongly identified that HMGB1 gene was a direct target of miR-142, and HMGB1 could attenuate miR-142-mediated inhibitory effects on the proliferation and invasion of cervical cancer cells as well as the expression of HMGB1 protein." (PMID 27829233, 2017). "Ectopic expression of HMGB1 could attenuate the inhibitory impact of miR-142 on the proliferation and invasiveness of cervical cancer cells." (PMID 27829233, 2017).